MYL4 (myosin light chain 4)
Description:
Regulatory light chain of myosin. Does not bind calcium.
Synonyms: PRO1957; ALC1; AMLC; GT1
Tractability: Small molecule: an approved drug acts on it. Antibody: the Human Protein Atlas places it where antibodies can reach.
Gene: Protein-coding gene on chromosome 17 (47,200,446 to 47,227,683, forward strand). Ensembl gene ENSG00000198336.
Subcellular location (Human Protein Atlas): Plasma membrane
Pathways (Reactome):
Muscle contraction: Striated Muscle Contraction
Gene Ontology:
Molecular function: actin filament binding; actin monomer binding; myosin II heavy chain binding; calcium ion binding
Biological process: cardiac muscle contraction; muscle contraction; regulation of the force of heart contraction
Cellular component: A band; cytosol; myosin II complex
Genetic constraint (gnomAD): Loss-of-function variants: 16 observed, 22.86 expected, observed/expected ratio (o/e) 0.7, 90% interval 0.47 to 1.06. The upper end of that interval is the gene's LOEUF score, 1.06, which puts it in group 4 of 6, group 1 being the genes least tolerant of losing a copy. Missense variants: 249 observed, 266.42 expected, observed/expected ratio (o/e) 0.93, 90% interval 0.84 to 1.04. Synonymous variants: 82 observed, 101.24 expected, observed/expected ratio (o/e) 0.81, 90% interval 0.68 to 0.97.
Homologues: Orthologues: macaque MYL4 (98% identical), chimpanzee MYL4 (97% identical), dog MYL4 (95% identical), pig MYL4 (95% identical), guinea pig MYL4 (92% identical), rat Myl4 (90% identical), mouse Myl4 (89% identical), rabbit MYL4 (88% identical), tropical clawed frog myl4 (82% identical), zebrafish myl4 (79% identical), zebrafish cmlc1 (76% identical), zebrafish zgc:163073 (64% identical), and 3 more. Paralogues in human: MYL3 (78% identical), MYL1 (68% identical), MYL6B (66% identical), MYL6 (59% identical).
Diseases named in the same sentence as MYL4 in open-access papers:
MYL4 is named in the same sentence as 39 diseases in open-access papers, as found by Europe PMC text mining. Sharing a sentence is not in itself a finding about the gene and the disease. The quoted sentences say what the papers report.
atrial fibrillation (10 papers, 2017 to 2025). A disorder characterized by an electrocardiographic finding of a supraventricular arrhythmia characterized by the replacement of consistent P waves by rapid oscillations or fibrillatory waves that vary in size, shape and timing and are accompanied by an irregular ventricular response. "It is hoped that this study can provide the basis for serum MYL4 as a biomarker for the prevalence and risk stratification of atrial fibrillation and further explore the mechanism of miR-106/MYL4 in atrial fibrillation." (PMID 35874900, 2022). "The relationship between the levels of serum miR-106 and MYL4 and the prevalence of atrial fibrillation and the score of atrial fibrillation thromboembolism risk stratification scoring system (cha2ds2) was compared between the two groups." (PMID 35874900, 2022). "Mutation of MYL4 can lead to atrial fibrillation in humans, and MYL4 mutant zebrafish displayed disruption of sarcomeric structure and atrial enlargement." (PMID 29236749, 2017). "Serum miR-106 and MYL4 levels are closely related to the prevalence of atrial fibrillation, which can reflect the risk of thromboembolism in patients with atrial fibrillation and can be used as a biological indicator to predict the prognosis of patients with atrial fibrillation." (PMID 35874900, 2022). "LMNA CMs had the greatest expansion of vCM1.2, enriched for genes encoding Ca2+ regulators and molecules with electrophysiologic functions, while RMB20 and LMNA genotypes had the highest expression of MYL4, a sarcomere protein associated with atrial fibrillation." (PMID 35926050, 2022). "MYL4 was mainly located in the cell membrane and the positive expression rate of MYL4 was 24.35% (28/115) in patients with atrial fibrillation and 64.35% (74/115) in patients with sinus rhythm." (PMID 35874900, 2022). "The level of serum miR-106 in patients with atrial fibrillation was significantly higher than that in the control group, whereas the level of MYL4 was significantly lower than that in the control group (P < 0.01)." (PMID 35874900, 2022). "With the increase of miR-106 level and the decrease of MYL4 level, the prevalence of atrial fibrillation gradually increased." (PMID 35874900, 2022). "With the increase of the severity of atrial fibrillation, the level of serum miR-106 gradually increased and the level of MYL4 gradually decreased, which were statistically significant compared with the control group (P < 0.05)." (PMID 35874900, 2022). "Like p.Gln254Pro in MYZAP, the three low-frequency missense and frameshift variants we have previously reported to increase the risk of atrial fibrillation, in MYH6, MYL4, and PLEC, also increase the risk of SSS8." (PMID 30271950, 2018). "Although previous studies have revealed that MYL4 gene mutation is closely related to familial atrial fibrillation and familial atrial quiescence, no report has focused on the relationship between serum MYL4 levels and atrial fibrillation." (PMID 35874900, 2022).
cardiomyopathies (9 papers, 2019 to 2025). "Pathogenic variants in MYL2, MYL3 and MYL4 genes cause various isolated cardiomyopathies." (PMID 40488356, 2025). "In addition, although the functions of MYL4 in cHF were poorly understood currently, variants of MYL4 have been shown as a causative factor in certain cardiomyopathy, especially in hypertrophic cardiomyopathy." (PMID 35203611, 2022). "Disruptions in these findings, due to mutations in genes like MYL4 and TTN, lead to cardiomyopathies and structural defects." (PMID 39202774, 2024). "MYL4 expression did not associate with sudden cardiac death or other cardiomyopathies." (PMID 31481666, 2019). "Both Myl4 and Sdha are highly expressed in BXD mouse hearts with a mean expression of 10.8 and 14.6, respectively, are significantly correlated with Rpl3l and are functionally related to cardiomyopathy." (PMID 38254943, 2023). "In other words, NPPA, MYL4, and PAM may serve as potential predictors and biomarkers for the diagnosis and prognosis of cardiomyopathy." (PMID 36034815, 2022). "In this second comparison, the percent of MYL4+ cells in septal tissue of HCM (N = 45) was not different in comparison to other forms of cardiomyopathy (p = 0.6, linear mixed model with age, sex and HCM)." (PMID 31481666, 2019).
hypertrophic cardiomyopathy (5 papers, 2019 to 2025). A condition in which the myocardium is hypertrophied without an obvious cause. "Higher MYL4 expression was also modestly associated with hypertrophic cardiomyopathy (p = 6.3e-04)." (PMID 31481666, 2019). "MYL4 is a cardiac gene whose expression is predominantly in the atria in healthy hearts but is overexpressed in the ventricles of failing hearts and is commonly found in hypertrophic cardiomyopathy, dilated cardiomyopathy, and ischemic heart disease." (PMID 40354360, 2025). "Interestingly, in patients with dilated and hypertrophic cardiomyopathy, a significant increase in MYL4 was observed, and it was hypothesized that this upregulation may be part of a compensatory mechanism." (PMID 32927262, 2020).
atherosclerosis (3 papers, 2019 to 2022). A disease characterized by the build-up of fatty material and calcium deposition in the arterial wall resulting in partial or complete occlusion of the arterial lumen. "Moreover, Pcb3, Cox5b, and Myl4 are involved in atherosclerosis, diabetic cardiomyopathy, and cardiac muscle contraction, respectively." (PMID 35479750, 2022).
cardiac arrhythmia (3 papers, 2022 to 2025). Any disturbances of the normal rhythmic beating of the heart or MYOCARDIAL CONTRACTION. "Overexpression of a transgenic construct containing the atrial-specific myosin light chain 4 gene MYL4 (OMIM: 160770) with the p.Glu11Lys mutation results in the development of arrhythmia." (PMID 40722594, 2025). "Zebrafish carrying myl4 or plakoglobin mutations have been used in small molecule screens to identify modifiers of cardiac arrhythmia, and have identified conserved disease mechanisms in both zebrafish and mammalian models." (PMID 35050223, 2022). "For example a loss of function in the MYL4 gene, which encodes an atria-specific myosin light chain, and a TTN gene mutation which codes a truncated variant of the giant sarcomeric protein titin predispose to early atrial fibrosis leading to cardiac arrhythmia." (PMID 36386377, 2022). "This study also established a significant genetic interaction between MYL4 mutant alleles and common risk alleles at the PITX2 locus, which is very interesting given the similar observations in pitx2c mutant larvae that display disorganized sarcomeres prior to the onset of cardiac arrhythmia." (PMID 35050223, 2022).
dilated cardiomyopathy (3 papers, 2019 to 2025). Cardiomyopathy which is characterized by dilation and contractile dysfunction of the left and right ventricles. "M1, associated with dilated cardiomyopathy and cardiac muscle contraction, contained enhanced proteins like Myl4, Trpm4, Irf3 in LV." (PMID 39921206, 2025).
familial atrial fibrillation (3 papers, 2016 to 2022). An autosomal dominant heart condition that causes disruptions in the heart's normal rhythm. "Another additional gene in AA was myosin light chain 4 (MYL4), a previously known atrial-specific myosin light chain, whose mutation causes familial atrial fibrillation." (PMID 32903789, 2020).
congenital heart disease (2 papers, 2022 to 2023). A heart disease that is present at birth. "MYL4 expression (encoding a fetal myosin light chain) can improve myocardial contractility and was found in a variety of congenital heart diseases and cardiomyopathies." (PMID 37481629, 2023). "Research has indicated that the expression of MYL4 in ventricular myocytes is reactivated, and its activation may be beneficial to improve cardiac systolic function in congenital heart disease and ventricular cardiomyopathy." (PMID 35874900, 2022). "In congenital heart disease and ventricular cardiomyopathy, MYL4 expression in ventricular myocytes is reactivated, and its activation may be beneficial for improving cardiac systolic function." (PMID 35874900, 2022).
heart failure (2 papers, 2025). Inability of the heart to pump blood at an adequate rate to meet tissue metabolic requirements. "Further, transgenic animal studies that overexpress MYL4 in the left ventricle found that fibers expressing high MYL4 levels exhibited higher maximal velocity and rate of fiber shortening and MYL4 overexpression attenuated heart failure in pressure-overloaded animals." (PMID 40354360, 2025).
ischemic heart disease (2 papers, 2019 to 2025). "In a linear mixed model, there was a weak signal for reduced percentage of MYL4+ cells in individuals dying of SCD with no coronary artery disease (p = 0.012)." (PMID 31481666, 2019).
end-stage renal disease (1 paper, 2025). "This study aims to provide new insights for the treatment of end-stage renal disease through a preliminary exploration of the correlation between the HBM and MYL4 gene loci and ESRD." (PMID 40619276, 2025).
Mitochondrial myopathy (1 paper, 2021). "Indeed, one term (GO:0033275) included three DEGs (ACTC1, MYL4, and TNNT2) with essential roles in muscle function, the former of which has also been shown to be overexpressed in mitochondrial myopathy due to mitochondrial respiratory chain deficiency." (PMID 34488775, 2021).
myopia (1 paper, 2026). "Our meta-analysis identified seven novel suggestive loci associated with myopia progression, including FSTL5 on 4q32.2, SMARCA2 on 9p24.3, CCDC3 on 10p13, GALNT6/ACVR1B on 12q13.13, CRY1 on 12q23.3, ULK2 on 17p11.2, and MYL4/EFCAB13-DT on 17q21.32." (PMID 42094695, 2026).
renal fibrosis (1 paper, 2025). A final common manifestation of a wide variety of chronic kidney diseases characterized by glomerulosclerosis and tubulointerstitial fibrosis. "Studies have found that increased expression of MYL4 may be related to the progression of renal fibrosis, suggesting that it may play an important role in the pathophysiology of ESRD." (PMID 40619276, 2025). "The interaction of MYL4 with the connexin protein Cx43 is believed to play an important role in atrial fibrosis, and this mechanism may also apply to the study of renal fibrosis." (PMID 40619276, 2025).
Right ventricular cardiomyopathy (1 paper, 2021). Right ventricular dysfunction (global or regional) with functional and morphological right ventricular abnormalities, with or without left ventricular disease. "Moreover, MYL4 detected by both bioinformatic and ML analysis, was already validated in a previous study, while ATP2A2 is reported to be associated to “arrhythmogenic right ventricular cardiomyopathy” pathway by KEGG." (PMID 34946895, 2021).
sarcoma (1 paper, 2011). A usually aggressive malignant neoplasm of the soft tissue or bone. "Indeed we found increased expression levels for RMS-markers (Myog, Myl4, Igf2, Prox1), a FS-gene (Vcan), and LS-related genes (Pparg, Myo1e, Hoxa5, Plau), which further established the MD-tumors as mixed sarcomas consisting of RMS, FS and LS-compartments." (PMID 21533183, 2011).
Thromboembolism (1 paper, 2022). The formation of a blood clot inside a blood vessel that subsequently travels through the blood stream from the site where it formed to another location in the body, generally leading to vascular occlusion at the distant site. "It was suggested that serum miR-106 and MYL4 could reflect the risk of thromboembolism in patients with AF, providing guidance for clinical treatment." (PMID 35874900, 2022). "In addition, this study analyzed the relationship between serum miR-106 and MYL4 and the risk stratification of thromboembolism in AF and found that with the increase of CHA2DS2 score, the level of serum miR-106 was increased, and the level of MYL4 was decreased." (PMID 35874900, 2022).
tongue tumor (1 paper, 2018). "The present study identified cofilins (CFL1 and CFL2) and tropomyosin family proteins (TPM3 and TPM4) are significantly upregulated, in contrast, myosin family proteins (MYL2, MYL4 and MYLPF) were downregulated in tongue tumor samples as compared to normal samples." (PMID 29371635, 2018). "Among 24 candidates, 8 proteins including Myosin light chain family members (MYLPF, MYL4 and MYL2), creatinine kinase, serotransferrin, heat shock protein A8, carbonic anhydrase 1 and Glyceraldehyde-3-phosphate dehydrogenase were significantly downregulated in tongue tumor tissues." (PMID 29371635, 2018).
type 2 diabetes (1 paper, 2025). "Importantly, a large number of sarcomeric proteins (such as myosin light chain kinase 2 [MYLK2], MYBPC2 and myosin light chain 4 [MYL4]) were downregulated in type 2 diabetes muscle fibres." (PMID 40295335, 2025).
cardiovascular disease (2 papers, 2014 to 2025). "The expression level of MYL4 is associated with various cardiovascular diseases, particularly in the processes of atrial fibrosis and cardiac remodeling, where its function is particularly important." (PMID 40619276, 2025).
neoplasm (2 papers, 2016 to 2025). A benign or malignant tissue growth resulting from uncontrolled cell proliferation. "While our literature research has not found any role of Myl4 in carcinogenesis, Peg3 has been reported to act like a tumor suppressor gene." (PMID 27461468, 2016).
kidney diseases (1 paper, 2025). "Research has shown that MYL4 may also regulate cell survival and death by affecting the intracellular autophagy process, a mechanism that plays an important role in the occurrence and development of kidney diseases." (PMID 40619276, 2025).
MYL4 also shares sentences with these, for which no sentence is quoted: cancer (2 papers); cardiac hypertrophy (2); Aortic root aneurysm (1); Arrhythmia (1); breast carcinoma (1); cardiac disease (1); coronary artery atherosclerosis (1); diabetic cardiomyopathy (1); dissection (1); Hypertension (1); leiomyosarcoma (1); malignant neoplasm of breast (1); muscular disease (1); myopathy (1); Paroxysmal atrial fibrillation (1); Peripheral arterial stenosis (1); squamous cell carcinoma of esophagus (1).